PARAL1 (PPARG activating RBM14 associated lncRNA 1)
Synonyms: NR_109
Gene: Long non-coding RNA gene on chromosome 20 (9,986,088 to 10,007,116, forward strand). Ensembl gene ENSG00000243961.
Diseases named in the same sentence as PARAL1 in open-access papers:
PARAL1 is named in the same sentence as 3 diseases in open-access papers, as found by Europe PMC text mining. Sharing a sentence is not in itself a finding about the gene and the disease. The quoted sentences say what the papers report.
Obesity (3 papers, 2017 to 2025). Accumulation of substantial excess body fat. "One clinical trial found that Paral1, a long intergenic noncoding RNA (lincRNA), is a novel biomarker of obesity-related dysregulation of adipose tissue function." (PMID 40732992, 2025). "In conclusion, we have identified a novel component of the adipogenic transcriptional regulatory network defining the lincRNA Paral1 as an obesity-sensitive regulator of adipocyte differentiation and function." (PMID 29075020, 2017). "Paral1 acts as an obesity-sensitive regulator of adipocyte differentiation and metabolic function." (PMID 40732992, 2025). "TNF stimulation of differentiated 3T3-L1 cells, mimicking part of the M1 macrophage-induced inflammatory response, decreased Paral1 expression, suggesting that obesity-induced inflammation may regulate Paral1 expression." (PMID 29075020, 2017). "Paral1 expression was therefore assessed in 2 mouse models of obesity." (PMID 29075020, 2017). "For example, users can input ‘obesity’ as the name of metabolic syndrome trait on the ‘SEARCH’ page and will find that a number of miRNAs and lncRNAs such as miR-21, miR-155-5p and Paral1 showed abnormal expression in human obesity." (PMID 31637139, 2019). "Expression studies in obese mice and humans showed a similarly decreased expression of Paral1 in obese WAT, thereby identifying a novel adipogenic pathway dysregulated in obesity." (PMID 29075020, 2017).
PARAL1 also shares sentences with these, for which no sentence is quoted: cancer (1 paper); metabolic syndrome (1).